WT1 (WT1 transcription factor)
Diseases named in the same sentence as WT1 in open-access papers (continued):
Sharing a sentence is not in itself a finding about the gene and the disease.
renal failure (32 papers, 2009 to 2025). "In a French cohort of DDS with WT1 variants in exon 8 and 9, it was demonstrated that 90% of the children reached kidney failure at a median age of 0.8 years and that there is a significant genotype-phenotype relationship in the presentation of DDS." (PMID 40890712, 2025). "We previously reviewed 174 cases with WT1 exon 8 and 9 missense variants and found that the median age of developing kidney failure was 0.90 in the DNA binding site group, 2.00 in the C2H2 site group, and 3.92 years in the other site group." (PMID 40493154, 2025). "In patients with WT1 variants (n = 13), those with CNS developed kidney failure earlier than those with infantile NS (0.5 vs. 9.1 months of age; P < 0.001)." (PMID 40095038, 2025). "The present study showed that all CNS patients with WT1 variants had missense variants in the DNA-binding site and developed kidney failure within the first 3 months of life." (PMID 40095038, 2025). "Previous studies showed that patients with WT1 missense variants in exon 8 or 9 developed kidney failure earlier than those with truncating or splice site variants, and the median age at kidney failure onset ranged from 0.22 to 2.5 years." (PMID 40095038, 2025). "From this viewpoint, not only heterozygous WT1+/− mice but also patients with one mutated WT1 allele, have a high risk of developing renal failure." (PMID 36834691, 2023). "Despite the expected high frequency of kidney failure in patients carrying WT1 pathogenic variants, to date, only seven (out of 25) patients required chronic dialysis." (PMID 34608521, 2022). "Gonadal dysgenesis with renal failure based on a WT1 mutation is possible in this patient who had a 46,XY karyotype and was yet to undergo a diagnostic laparotomy/laparoscopy." (PMID 31871452, 2019). "Mutations in the WT1 gene are associated with the development of renal failure due to the formation of scar tissue within glomeruli, the mechanisms of which are poorly understood." (PMID 29398135, 2018). "The second individual, RaPS_11, who presented with renal failure, was found to have a de novo WT1 mutation." (PMID 30049826, 2018). "WT1 mutation is a known risk factor for DSD with early renal insufficiency and kidney tumors." (PMID 38337479, 2024). "However, the potential for knowledge of the WT1 pathogenic variant to accurately predict kidney function longevity will require larger numbers of children presenting with cancer or kidney failure to be systematically screened for WT1 pathogenic variant." (PMID 34608521, 2022). "Additionally, the rapid progression of renal failure associated with WT1 mutations may have contributed to this case." (PMID 41142893, 2025). "In addition to germ cell loss, inactivation of Wt1 in adult mice also resulted in multiple phenotypes, including accumulation of ascitic fluid, atropic spleen, abnormal pancreas, and renal failure, consistent with a previous report." (PMID 23935527, 2013). "The role of WT1 abnormalities in kidney and renal failure development has previously been described." (PMID 34970513, 2021). "Consistently, overexpression of miR-671-5p accelerates 5/6NX-induced podocyte injury and renal insufficiency, whereas miR-671-5p antagomir restores WT1 and prevents the progression of ADR nephropathy." (PMID 35111054, 2021). "It is well known that WT1 is abundantly expressed in renal glomerular podocytes (or visceral epithelial cells) and that dysfunction of podocytes results in severe renal failure." (PMID 24393438, 2014). "In this context, WT1 is vital for the proliferation of renal progenitor cells; it directly influences the development of embryonic nephrons and promotes the regeneration of renal proximal tubules after acute kidney injury." (PMID 40940806, 2025). "In addition, WT1 gene-deletion mice exhibit defective podocyte differentiation, anuria, and renal failure; therefore, WT1 is considered essential for kidney development." (PMID 38073545, 2023).
renal failure (continued). "In this case, exosomal Wilm’s tumor-1 (WT1) mRNA from urine sediment of DN patients is inversely associated with estimated glomerular filtration rate (eGFR), indicating glomeruli damage and early renal failure." (PMID 35363774, 2022). "The WT1 variant with a mutation in ZF9 may disrupt podocyte development and differentiation, leading to renal insufficiency." (PMID 33942367, 2021). "Among WT1-related disorders, NPHS4 was considered the etiology of the patient's renal failure." (PMID 32843431, 2020). "Herein, we demonstrated that WT1+ PECs were activated and proliferated in mice with acute renal failure and ultimately developed into mature PTECs after severe AKI." (PMID 36923529, 2023). "Interestingly, neither aberrant sex determination nor renal failure was noted in the NOA patients carrying WT1 mutations." (PMID 23935527, 2013). "Nephrin, podocin and WT-1 play important roles in maintaining the integrity of GFB, and decreases in their expression can result in podocyte apoptosis, detachment and fusion, ultimately leading to symptoms of renal insufficiency, such as proteinuria." (PMID 39080783, 2024). "Therefore, in conclusion, adoptive transfer of WT1-specific CTLs in patients without renal failure is likely safe; however, it should be performed cautiously in patients with proteinuria." (PMID 24393438, 2014). "Similarly, mice with complete absence of WT1(+KTS) develop abnormal podocyte morphology and impaired foot process formation leading to renal failure." (PMID 19652713, 2009).
serous ovarian carcinoma (31 papers, 2006 to 2026). "WT-1 (Wilms Tumor 1) is a transcription factor and plays an essential role in the normal development of the urogenital system and 93% of ovarian serous carcinomas showed to express nuclear staining for WT-1." (PMID 34314463, 2021). "WT1 is a nuclear marker expressed in a heterogeneous tumour group such as malignant mesothelioma, serous ovarian carcinoma or round cell desmoplastic tumour." (PMID 29621151, 2018). "It was well documented that WT1 and ER expression was commonly present in ovarian serous carcinomas with a frequency of approximately 90 %, and very unusual in endometrial serous carcinoma." (PMID 27260518, 2016). "WT1 and CA-125 are expressed in the majority of ovarian serous carcinomas, but the majority of ovarian clear cell and mucinous carcinomas are negative for the markers." (PMID 24137345, 2013). "Ovarian serous adenocarcinomas exhibit positive immunostaining with WT1 while endometrial serous carcinomas and both ovarian and endometrial endometrioid adenocarcinomas show negative immunostaining with WT1." (PMID 22371431, 2012). "WT-1 immunohistochemical expression was shown in majority of serous carcinomas of ovary, fallopian tube as well as PPSC establishing as a highly sensitive as well as specific marker for tumors of mullerian differentiation." (PMID 21826275, 2011). "This is the first report that demonstrates the prognostic significance of WT1 gene expression in serous ovarian carcinoma." (PMID 16606472, 2006). "WT1 IHC positivity in peritoneal fluid pointed toward serous carcinoma of the ovary." (PMID 36938247, 2023). "The transcription factors MECOM, PAX8, SOX17 and WT1 are candidate master regulators of high-grade serous 'ovarian' cancer (HGSC), yet their cooperative role in the hypothesized tissue of origin, the fallopian tube secretory epithelium (FTSEC) is unknown." (PMID 37090516, 2023). "WT1 protein is proposed as a nuclear marker for serous ovarian cancer." (PMID 30018258, 2018). "Similarly to Her-2/neu, WT1 is expressed in a wide spectrum of hematological and solid tumors, including high-grade serous ovarian cancer." (PMID 27323861, 2016). "Ovarian serous carcinoma is a known WT1 protein immunohistochemical (IHC) staining positive tumor where WT1 is used for histopathological classification 19–23 but as a prognostic factor WT1 expression may be of limited value 24–26." (PMID 24715586, 2014). "In the present study, we could demonstrate the immunohistochemical expression of WT1 gene in advanced serous ovarian carcinomas." (PMID 16606472, 2006). "We found that about 50% of advanced serous ovarian carcinoma patients were reactive for WT1." (PMID 16606472, 2006). "Moreover, in gynecological pathology, the immunohistochemical expression of WT1 is useful in the diagnosis of ovarian serous carcinoma (both high grade and low grade histotypes) and is also helpful to distinguish carcinoma of ovarian origin from carcinoma with other primary sites." (PMID 32859123, 2020). "Moreover, WT1, which are expressed by mesothelial, ovarian (granulosa) and renal glomerular cells, are of interest for CUPs based on the high sensitivity and specificity (>90%) in serous carcinomas of the ovary." (PMID 29621151, 2018).
serous ovarian carcinoma (continued). "The 6 papillary CNS metastases had a complete prior workup with IHCs confirming their origin, such as TTF1 and thyroglobulin for papillary thyroid carcinoma, TTF1, CK7, CK20 for lung adenocarcinoma, and Pax8, WT1, CK7, CK20 for serous carcinoma of the ovary." (PMID 27229317, 2016). "As expected, the initial tumor and all the models harbored nuclear expression of PAX8, a marker for carcinoma of Müllerian origin, and no expression of WT1, a robust prognostic marker selectively expressed in some high-grade serous ovarian carcinoma." (PMID 37803448, 2023). "Immunohistochemical staining was positive for CK-7 and WT-1, and negative for CK-20, suggesting that the tumor was not bile duct cancer but metastasis from ovarian serous adenocarcinoma." (PMID 31222668, 2019). "Wilms’ tumor protein (WT1) is regularly expressed not only in malignant mesotheliomas but also in ovarian serous carcinomas and thus is not suitable to distinguish these tumour entities." (PMID 26197800, 2015). "Expression of Wilm’s Tumour (WT1), known to be primarily expressed in serous ovarian cancers, was seen in all serous patients, and absent in patient 61 (data not shown)." (PMID 26440065, 2015). "Cancer cells of this type show serous papillary morphology, and are positively immunostained for Ber-EP4 and WT1, and indistinguishable from serous ovarian cancers by cytology and immunohistochemistry." (PMID 24213462, 2012). "WT1 reactivity is limited to ovarian serous carcinomas, and is not found in mucinous carcinomas." (PMID 16606472, 2006). "However, the relationship of WT1 expression in serous ovarian carcinoma with adverse outcome had not previously been reported." (PMID 16606472, 2006).
acute leukemia (28 papers, 2006 to 2025). A clonal (malignant) hematopoietic disorder with an acute onset, affecting the bone marrow and the peripheral blood. "As evident by the results of the current study and also many others, it is well established that the wild-type WT1 protein is highly expressed in acute leukemia, even in patients with WT1 mutations." (PMID 37444601, 2023). "Several studies indicated that WT1 overexpression is an independent risk factor for relapse in acute leukemia." (PMID 26740869, 2016). "Our findings were in contrary to other studies which identified WT1 overexpression as an independent adverse prognostic factor in acute leukemia associated with an increased risk of relapse." (PMID 27275197, 2015). "By contrast, WT1 is highly expressed in most acute leukemias and its level of expression is associated with the presence, persistence, or reappearance of leukemic hematopoiesis." (PMID 27275197, 2015). "Recently, immunological approaches to inactivate WT1 in acute leukemia and high-risk MDS have been proposed: these studies provided preliminary evidences of potential clinical efficacy in these patients." (PMID 22964015, 2012). "To date, WT1, BIRC5, and PRAME have not been promoted as biomarkers of relapse, likely in part due to the scant data for BIRC5 and PRAME and the lack of sensitivity for detection of relapse in prior studies of WT1 in acute leukemia." (PMID 36248870, 2022). "WT1 has been reported to be expressed in acute leukemias and in several lymphomas, including ALK+ sALCLs (3/6, 50%), ALK− sALCLs (14/31, 45%) and cALCLs (1/6, 17%)." (PMID 34944796, 2021). "The WT1 expression and serum levels of IL-12 and C3 complement were assessed among Iranian acute leukemia patients compared with healthy controls." (PMID 32375828, 2020). "It was shown that there was significant WT1 over expression, while significant decreased serum levels of IL-12 and C3 in acute leukemia patients compared with controls." (PMID 32375828, 2020). "The Wilms’ tumor (WT1) gene has been demonstrated to be a sensitive molecular marker in acute leukemias, myelodysplastic syndromes, and myeloproliferative disorders." (PMID 27167495, 2016). "Differential expression between acute leukemia patients and healthy volunteers suggests that the immunogenic antigens (PRAME and WT1) are potential candidates for immunotherapy in childhood acute leukemia." (PMID 27275197, 2015). "WT1 expression is considered an unfavorable prognostic marker in acute leukemia and WT1 expression is also detected in S-ALCL; however, the prognostic value of BCL-2, WT1, and Ki-67 in S-ALCL remains to be determined." (PMID 22769020, 2012). "The role of WT1 as an unfavorable prognostic marker has been confirmed in acute leukemia and some of solid tumors." (PMID 22769020, 2012). "Real-time PCR was performed as confirmational experiments to verify the WT1 mRNA over expression in the patients with acute leukemia." (PMID 19662212, 2007). "The current study was designed to investigate the WT1 gene expression status in local adult patients with acute leukemia." (PMID 19662212, 2007). "WT1 gene has been shown to be universally expressed in various types of malignant blood disorders, such as acute leukemia, chronic granlocytic leukemia, multiple myeloma, etc." (PMID 19662212, 2007). "We were also exploring the possible clinical application of WT1 as a molecular marker in adult patients with acute leukemia." (PMID 19662212, 2007). "In the study, we have used the Wilms’ tumor gene (WT1) as a biomarker to evaluate its expression in local adult patients with newly diagnosed acute leukemia, including both acute myeloid and lymphoid leukemias (AML and ALL)." (PMID 19662212, 2007). "The WT1 mRNA levels from all 18 patients with acute leukemias was 41.39 ± 36.20% in comparison to K562 cells." (PMID 19662212, 2007). "In conclusion, WT1 gene was universally expressed in local adult patients with acute leukemia at diagnosis in Singapore." (PMID 19662212, 2007).
acute leukemia (continued). "WT1, a transcription factor involved in normal embryonic development of urogenital and hematopoietic systems, plays an important role in pathogenesis of hematologic malignancies, especially acute leukemias." (PMID 33395407, 2021). "The expression of Wilms tumor-1 (WT1), brain and acute leukemia, cytoplasmic (BAALC) and ETS-related gene (ERG) might be considered as prognostic factors in AML patients." (PMID 33747867, 2021). "In addition, as already demonstrated in acute leukemias, there is a strict correlation between WT1 at diagnosis in BM and PB samples." (PMID 27167495, 2016). "Moreover, T cells stimulated with the peptide WT1J-W4WF were able to recognize the native WT1J sequence and showed cytotoxicity against an HLA-A0201, WT1+ acute leukemia cell line." (PMID 19079589, 2008). "A number of reports have shown that WT1 gene could be used as a molecular marker for diagnosis, monitoring clinical progress in acute leukemia, and more importantly, as a molecular target for adoptive immunotherapy." (PMID 19662212, 2007). "In contrast they found high levels of WT1 in the peripheral blood and bone marrow samples from acute leukemia patients at diagnosis and that the WT1 transcript levels followed the pattern of other molecular markers, such as fusions transcripts, used in current MRD monitoring protocols." (PMID 19662193, 2007). "WT1 gene expression was observed in local patients with acute leukemia at diagnosis." (PMID 19662212, 2007). "WT1 may decrease serum levels of IL-12 and C3 in Iranian acute leukemia patients." (PMID 32375828, 2020). "The candidate targets of Wilms tumor 1 (WT1), survivin (BIRC5), and PRAME were selected given the high prevalence in relapsed and refractory acute leukemias (77-81% for WT1, 63-100% for BIRC5, and 42-87% for PRAME)." (PMID 36248870, 2022). "In patients with active acute leukemia after HCT (MRD+ or relapse; n=19), the blood levels of WT1/ABL1, PRAME/ABL1, and BIRC5/ABL1 exceeded healthy donors (p<0.0001, p=0.0286, and p=0.0064 respectively)." (PMID 36248870, 2022). "WT1 overexpression is observed in the majority of acute leukemias (~90% of pediatric AML cases), as well as various solid tumors, making WT1 an obvious vaccine target." (PMID 29867960, 2018). "In contrast to acute leukemia, mononuclear cells from bone marrow or peripheral blood of healthy volunteers did not express the WT1 gene at detectable levels." (PMID 35495123, 2022). "Constitutive expression of wild-type or mutant WT1 has been demonstrated in variety of hematologic malignancies and, particularly, in blasts of nearly all acute leukemias irrespective of lineage-specificity." (PMID 27275197, 2015). "Unlike its role in acute leukemia, WT1 was not a significant prognostic factor in S-ALCL in our study." (PMID 22769020, 2012). "Unlike the universal expression of WT1 gene, the HLA genotyping in this cohort of adult acute leukemia patients was heterogeneous." (PMID 19662212, 2007). "We hypothesized that a blood-based multiplex ddPCR assay of WT1, BIRC5 (survivin), and PRAME as a ratio against homeostatic ABL1 would detect MRD in the majority of relapsed refractory acute leukemias after HCT, at levels exceeding those of healthy individuals." (PMID 36248870, 2022). "However more studies on larger number of patients are needed for better understanding the roles of WT1 and PRAME genes in the process of leukemogenesis, their significance as a prognostic factor, minimal residual disease marker and being a possible target for immunotherapy in acute leukemia." (PMID 27275197, 2015). "It is concluded that the expression of PRAME and WT1 genes are indicators of favorable prognosis and can be useful tools for monitoring minimal residual disease (MRD) in acute leukemia especially in patients without known genetic markers." (PMID 27275197, 2015).